RNU6-144P (RNA, U6 small nuclear 144, pseudogene)
Gene: Small nuclear RNA gene on chromosome 8 (137,105,352 to 137,105,458, forward strand). Ensembl gene ENSG00000206678.
Homologues: Orthologues: chimpanzee U6 (97% identical), macaque U6 (91% identical), guinea pig U6 (79% identical), guinea pig U6 (77% identical), guinea pig U6 (76% identical), pig U6 (75% identical), guinea pig U6 (73% identical), guinea pig U6 (72% identical), guinea pig U6 (70% identical). Paralogues in human: RNU6-16P (95% identical), RNU6-1 (94% identical), RNU6-2 (94% identical), RNU6-20P (94% identical), RNU6-3P (94% identical), RNU6-4P (94% identical), RNU6-5P (94% identical), RNU6-6P (94% identical), RNU6-9 (94% identical), RNU6-12P (93% identical), RNU6-13P (93% identical), RNU6-17P (93% identical), and 1288 more.